PTX3 (pentraxin 3)
Diseases named in the same sentence as PTX3 in open-access papers (continued):
Sharing a sentence is not in itself a finding about the gene and the disease.
cardiovascular disease (continued). "Several studies have examined why plasma PTX3 levels are increased in patients with cardiovascular disease, and those that have targeted the PTX3 gene in mice suggest that plasma PTX3 levels may increase in order to confer protection against cardiac tissue damage." (PMID 22347626, 2012). "In recent years, research on PTX3/hs-CRP and metabolic syndrome, cardiovascular disease, and DM/DM-related complications has been increasing, but the results of various studies are inconsistent, and some are even contradictory." (PMID 31721795, 2019). "PTX3 can be released by neutrophils early and by macrophages and endothelial cells in the late phase of myocardial infarcted patients and there is evidence to suggest that the heart is a major site for PTX3 expression, which could contribute to its involvement in multiple cardiovascular disorders." (PMID 31354697, 2019). "Cardiovascular diseases (CVD) are responsible for high number of deaths in the developed world and numerous studies have indicated that PTX3 has a potential contribution to prevent the progression of CVD." (PMID 31354697, 2019). "C-reactive protein (CRP), serum amyloid P component (SAP) and pentraxin 3 (PTX3) are all pattern recognition proteins belonging to the pentraxin super family, where CRP is a well established plasma marker for cardiovascular disease." (PMID 24060373, 2013). "Some peripheral cytokines frequently studied in cardiovascular disease such as matrix metalloproteinase-1 (MMP-1), matrix metalloproteinase-3 (MMP-3), osteopontin, and pentraxin-3 can be used as markers to reflect vascular inflammation, endothelial function, or permeability of the BBB." (PMID 38581060, 2024). "In the CHS (Cardiovascular Health Study), the geometric mean±SD for PTX3 in subjects without prevalent cardiovascular disease (CVD) was 1.64±1.8 ng/mL." (PMID 29650706, 2018). "So, up to now we can consider that several new nontraditional markers as CD40-CD40 ligand system and pentraxin-3 seem to be significant features of cardiovascular disease in general and in ESRD population." (PMID 22701810, 2012). "However, the relative contribution of pentraxin‐3 (PTX‐3), a novel marker for inflammatory cardiovascular disease, in the hypertrophic response to pressure overload has not been adequately elucidated." (PMID 39414396, 2024). "Despite these observations, the negative association between PTX3 and HELP LDL apheresis vintage suggests that chronic intensive lipid-lowering with HELP LDL apheresis has beneficial effects in patients with extensive cardiovascular disease." (PMID 25014007, 2014). "However, PTX3 is not a specific marker for bacterial infections, which is why we adjusted our analysis for comorbidities, such as cardiovascular disease and malignancy, where high PTX3 levels have been shown to be correlated with disease severity and mortality." (PMID 26880104, 2016). "SAT PTX3 mRNA expression correlated with plasma PTX3 concentrations (rho = 0.54, p = 0.0001) and was increased (3.7 [0.4–70.3] vs. 1.2 [0.2–49.3] RQ, p = 0.02) in CKD patients with cardiovascular disease (CVD), but was not significantly different between patients and controls." (PMID 23658833, 2013).
infectious disease (27 papers, 2011 to 2026). A disorder directly resulting from the presence and activity of a microbial, viral, or parasitic agent in humans. "Quantification of circulating PTX3 levels demonstrates potential as an adjunctive biomarker for the diagnosis of infectious diseases and holds considerable value in early risk stratification, precise disease assessment, and personalized therapeutic strategies." (PMID 41800408, 2026). "This review systematically summarizes recent advances in the diagnostic significance and immunoregulatory mechanisms of PTX3, providing new insights into overcoming current challenges in the precision diagnosis and treatment of infectious diseases." (PMID 41800408, 2026). "Although longitudinal data in human VL are scarce, our findings align with evidence from other infectious diseases showing that PTX3 reflects systemic inflammation and, in some settings, treatment response." (PMID 41471254, 2025). "This would enhance the interpretation of Ptx3 findings in human samples and facilitate its application as a biomarker of infectious diseases in clinical settings." (PMID 40576635, 2025). "Its interactions with C1q, factor H, and other complement components place PTX3 at a central position in regulating inflammatory cascades, explaining its consistent upregulation across infectious diseases." (PMID 41471254, 2025). "Our objective is to highlight the potential for clinical targeting of PTX3 as a biomarker in infectious diseases and to propose it as a viable alternative in future therapeutic strategies." (PMID 40313930, 2025). "This is in line with earlier research on the use of the PTX3 level to predict the severity of infectious diseases." (PMID 39294659, 2024). "Due to the participation of PTX3 in the inflammatory response, it has a crucial role in infectious diseases (their occurrence and progression) and different clinical conditions." (PMID 39062835, 2024). "PTX-3 is a new type of acute-phase inflammatory factor and plays an important role in infectious diseases." (PMID 39021820, 2024). "PTX3 has the ability to modulate the innate immune response involved in protection against infectious diseases, and it acts in the regulation of complement activation, opsonization of pathogens and apoptotic cells." (PMID 38053036, 2023). "PTX3 was investigated as a biomarker in infectious diseases and has emerged as a powerful independent predictor of mortality as recently described in SARS-CoV2 syndrome." (PMID 35204613, 2022). "PTX3 is a molecule known for its involvement in modulating the mechanisms of innate immunity, which come into play to protect the body from infectious diseases." (PMID 34073015, 2021). "Pentraxin 3 (PTX3) is a glycoprotein belonging to the humoral arm of innate immunity that participates in the body’s defence mechanisms against infectious diseases." (PMID 34073015, 2021). "Some studies have suggested that the serum PTX-3 expression level is low in the healthy population but increases significantly in patients with inflammation and infectious disease." (PMID 35059041, 2021). "Pentraxin-3 (PTX3), as an essential component of innate immunity, is upregulated in various infectious diseases." (PMID 34679604, 2021). "Since its discovery, PTX3 has been described to modulate innate immune mechanisms involved in protection against infectious diseases." (PMID 31031772, 2019). "PTX3 also binds to a wide range of microorganisms, including fungi, bacteria, and viruses and is involved in resistance to selected infectious diseases." (PMID 31031772, 2019). "High expression of PTX3 was noted in diverse infectious disorders including sepsis, tuberculosis, dengue infection, and autoimmune disorders." (PMID 25797258, 2015). "Recent studies have shown that PTX3 can be used as a marker for disease severity and fatal outcome in cardiovascular, inflammatory and infectious diseases." (PMID 24039869, 2013).
infectious disease (continued). "The present results thus confirm those of previous studies on the prognostic value of PTX3 in infectious diseases." (PMID 21423699, 2011). "Additionally, this study contributes valuable support for the use of PTX3 as a diagnostic marker in suspected cases, akin to the way CRP is employed in clinical practice for infectious diseases." (PMID 38053036, 2023). "The findings suggest a potential role of PTX3 in infectious diseases." (PMID 25797258, 2015). "Thus, our results support recent findings on PTX3 in infectious disorders and thereby emphasize the potential of PTX3 as an important prognostic marker in ICU patients." (PMID 24039869, 2013). "The precise clinical implications of PTX3 in infectious diseases remain elusive." (PMID 21423699, 2011). "Additionally, plasma PTX3 has emerged as a potential biomarker for various infectious diseases." (PMID 38053036, 2023). "Long pentraxin 3 (PTX3), a key acute-phase reactant protein and soluble pattern recognition receptor (PRR), has recently garnered considerable attention for its role in infectious diseases." (PMID 41800408, 2026).
bacterial infection (23 papers, 2008 to 2025). "PTX3 is associated with bacterial infection in patients with COPD, but its utility as a biomarker for identifying a bacteria-associated exacerbation warrants further studies." (PMID 28458531, 2017). "Nevertheless, we found significantly higher levels in the patients with NSTI underlining PTX3 as a marker of bacterial infection." (PMID 26880104, 2016). "However, in our study, CLU, which seems more closely associated with qSOFA, appears to be more closely linked to all‐cause severity, whereas PTX3 is associated with the 2001 classification and the presence of a confirmed bacterial infection." (PMID 40722110, 2025). "Elevated PTX3 levels appeared to be associated with bacterial infection during FN." (PMID 40722110, 2025). "Therefore, to increase practical implications, we performed a post hoc analysis limited to proven bacterial infections that confirmed the diagnostic accuracy of PTX3 levels in BAL fluid." (PMID 25314919, 2014). "Collectively, these studies advance our understanding of immune response due to bacterial infections and highlights PTX3 as a potential target for therapeutic strategies to control bacterial infections." (PMID 40313930, 2025). "Similar to other bacterial infections, PTX3 levels have been found to correlate with the progression of K. pneumoniae infection." (PMID 40313930, 2025). "CSF PTX3 was significantly higher among all CNS infections and undetectable in most of the patients in the control group, and significantly higher in bacterial infections compared to viral and Lyme infections." (PMID 36862691, 2023). "It was demonstrated that PTX3 is stimulated by IFN-gamma and is up-regulated by a number of viral and bacterial diseases, such as infectious bursal disease, avian pathogenic Escherichia coli (APEC), and Marek’s disease." (PMID 34759833, 2021). "PTX3 can be used as a marker to detect the health of chickens, with the expression of PTX3 known to increase in chickens after viral and bacterial infection." (PMID 35052428, 2021). "Further studies on the function of monocyte‐produced PTX‐3 during bacterial infection and the effects of CN inhibition in this context are now warranted." (PMID 30934147, 2020). "We aim to investigate if sputum PTX3 can be used as a biomarker for bacterial infection in subjects with COPD." (PMID 28458531, 2017). "PTX3 is involved in the initial response of mammary tissue to bacterial infection, and is thought to activate the immune system by binding both micro-organisms and C1q, the first component of the classical pathway of complement activation." (PMID 23046560, 2012). "Furthermore, studies measuring PTX3 levels in the plasma of patients with bacterial infections and aseptic meningoencephalitis revealed significantly higher PTX3 levels in those with bacterial infection." (PMID 40313930, 2025). "Since one of the most important roles for pentraxins is against bacteria, the overexpressed PTX3 by LXR in nasal mucosa could contribute to defense of bacterial infections." (PMID 33503887, 2021). "We analyzed RNA-seq data from various studies addressing the acute phase response in chickens and thereby detected a PTX3 up-regulation in a number of highly relevant viral and bacterial diseases, including IBDV, APEC, and GaHV2, the pathogen inducing Marek's Disease." (PMID 30774632, 2019). "At D0, PTX3 levels were significantly higher in patients with an identified bacterial infection (0.98 ng/mL) than in patients without identified bacterial infection (0.67 ng/mL) (p < 0.05)." (PMID 40722110, 2025). "PTX3 in the CSF can distinguish bacterial infection from viral and Lyme infections and non-CNS infections." (PMID 36862691, 2023). "It is important to note that PTX3 is not a specific marker for bacterial infection." (PMID 23341967, 2013).
bacterial infection (continued). "S100A12 and PTX3 mRNAs were markedly up-regulated in bMEC stimulated with LPS and LTA indicating that they may be involved in the initial response of mammary tissue to bacterial infection." (PMID 18513449, 2008).
inflammation (17 papers, 2013 to 2025). Aberrant reaction of the microcirculation characterized by movement of fluid and leukocytes from the blood into extravascular tissues. "A significant increase in inflammatory cytokines, such as IL-1β and IL-8, an indicator of local vascular inflammation, and pentraxin 3, a molecular marker of endothelial cell dysfunction, were also observed, supporting our experimental findings of dysfunctional CB-ECFCs upon serum deprivation." (PMID 37239042, 2023). "Hence, diagnostic or prognostic criteria could be clinically correlated with PTX3 expression in the pathogenesis of pulpal inflammation, which could lead to the identification of new markers for pulp inflammation." (PMID 31744201, 2019). "Therefore, PTX3 is a more accurate marker of the actual inflammatory state and mirrors local inflammation that does not necessarily lead to an increase in systemic cytokines (e.g., in vascular inflammation, even without systemic inflammation)." (PMID 31703088, 2019).
metabolic disorders (13 papers, 2014 to 2025). "The expression and balance of PTX3 play an important role in the occurrence and development of metabolic diseases." (PMID 28770376, 2017). "The scope of this review is to correlate the impact of PTX3 in DM and progression of complications, as well as antidiabetic drugs’ influence, considering that inflammatory pathways are pillars in the evolution of this metabolic disease." (PMID 40299501, 2025). "At the same time, it is rarely reported on PTX3/hs-CRP and GDM patients, a special population with high risk of secondary metabolic disorders, and whether hs-CRP and PTX3 have synergy in the occurrence of diseases is still unclear." (PMID 31721795, 2019). "For example, a proatherogenic role has been suggested for PTX3 in metabolic diseases." (PMID 31316299, 2019). "Evidence suggests that PTX3 serves as a biomarker of atherosclerosis and metabolic disorders." (PMID 28489600, 2017). "PTX3 activates and regulates the complement cascade by interacting with C1q and Factor H; therefore, it plays a non-redundant role in the resistance against selected microbes, cancer, tissue remodeling, and metabolic disease and in the regulation of inflammation." (PMID 28770376, 2017).
vasculopathy (8 papers, 2011 to 2021). "Endothelial cells are a major source of PTX3 and increased levels are reported for various vasculopathies." (PMID 34632327, 2021). "Pentraxin 3 (PTX3) is reported to be a vascular inflammation marker providing prognostic information of vasculopathy." (PMID 29715313, 2018). "Therefore further translational studies on plasma levels of PTX3 in the context of radiation-induced vasculopathy are needed." (PMID 24060373, 2013). "The sustained expression of PTX3 in arteries and veins tie biological evidence in humans to clinical studies and encourage further exploration of innate immunity in the pathogenesis of a radiation-induced vasculopathy." (PMID 24060373, 2013). "In good agreement with recent studies on radiation induced-vasculopathy, this rapid induction of plasma PTX3 levels could be attributed directly to the inflammatory response of vascular cells along with fibroblasts, epithelial cells, and endothelial cells undergoing irradiation." (PMID 27893415, 2016). "The PTX3 could influence the development of autoimmune reactions and vascular disorders in humans." (PMID 21978410, 2011).
kidney disease (7 papers, 2011 to 2025). "In humans PTX3 has been shown to correlate with surrogate markers of disease severity in cardiovascular and renal diseases and molecular characterization of this association suggests that PTX3 is involved in the fine tuning of inflammation with an overall tissue-protective effect." (PMID 30858847, 2019). "Moreover, PTX3 has been shown to predictthe risk of developing CKD and cardiovascularevents in patients with kidney diseases.PTX3's impact varies based on clinical circumstances,but its role in NS remains unexplored." (PMID 39139165, 2024). "PTX3 can aggravate kidney disease during inflammation, with studies showing that decreased renal function may be associated with higher PTX3 levels in patients with CKD." (PMID 34211440, 2021). "Hence, lack of PTX3 specifically accelerated the evolution of autoimmune lung disease, albeit not kidney disease, in B6lpr mice." (PMID 21637713, 2011).
heart disease (5 papers, 2019 to 2025). "Literature reports indicate that PTX3 is a significant factor contributing to cardiac dysfunction in various heart diseases." (PMID 40093897, 2025).
retinopathy (5 papers, 2021 to 2025). "PTX3, an acute-phase protein and marker of vascular injury, has proven to be significantly elevated in the aqueous humor of diabetic patients with retinopathy, especially in those diagnosed with the proliferative form of the disease." (PMID 40299501, 2025). "It appears, however, that PTX3 local levels in the aqueous humor of DR patients are higher than those in diabetic patients with no retinopathy or nondiabetic volunteers." (PMID 39348530, 2024). "Therefore, PTX3-dependent inhibition of angiogenesis (e.g., via binding and sequestration of FGF2) in the ischemic DR may drive disease progression (rather than regression) to proliferative retinopathy." (PMID 35069222, 2021).
connective tissue disease (4 papers, 2012 to 2025). "Recently it was shown that PTX3 could reflect any pathophysiological aspect for PAH, especially in patients with connective tissue disease." (PMID 25412085, 2014).
kidney (4 papers, 2015 to 2024). "We found that PTX3 protects kidney cells during ischemia and proinflammatory acute kidney injury." (PMID 29672566, 2018). "Recent studies have determined that PTX3 does not cause a negative effect on kidney damage, and, on the contrary, high PTX3 levels are an important marker of the immune inflammatory response and anti-inflammatory defense mechanism, which probably has a positive effect on the kidneys." (PMID 39697970, 2024).
neurological disease (3 papers, 2016 to 2026). "Another study representing the first transcriptome sequencing study proposed the association of seven genes (CTSS, SERPINA1, NPTX1, PTX3, CHI3L1, SERPINA3, and MX1) as “the missing link” to explain the correlation between HHV-6A infection and neurological diseases." (PMID 35683449, 2022). "In conclusion, based upon the results of our comprehensive analysis of HHV-6A infected HA1800 cells, we revealed several genes correlated with neurologic disorders, especially CTSS, PTX3, CHI3L1, Mx1, CXCL16, BIRC3, and BST2 genes." (PMID 27344170, 2016).
adenocarcinoma (2 papers, 2019 to 2021). A common cancer characterized by the presence of malignant glandular cells. "Patients with genotype GG in PTX3 rs1840680 also had a higher chance to have adenocarcinoma as compared to those with GA/AA (OR for adenocarcinoma: 0.23, 95% CI: 0.06-0.88, GA/AA vs GG)." (PMID 33967610, 2021). "Compared with CA/AA and GA/AA, patients with genotype CC in PTX3 rs2120243 and genotype GG in rs1840680 were more likely to develop adenocarcinoma." (PMID 33967610, 2021).
brain diseases (1 paper, 2018). "A glia-derived Pentraxin 3 (PTX3) expressed in the microglial secretome, has been seen to modulate phagocytic functions of microglia having crucial implications in the regulation of microglial activity in brain diseases." (PMID 29755398, 2018).
hematological cancers (1 paper, 2025). "PTX3 is a newly identified marker linked to negative outcomes in hematological cancers." (PMID 40426926, 2025).